IL6 (interleukin 6)
Diseases named in the same sentence as IL6 in open-access papers (continued):
Sharing a sentence is not in itself a finding about the gene and the disease.
Pruritus (26 papers, 2020 to 2026). Pruritus is an itch or a sensation that makes a person want to scratch. "It has been reported that IL-6 upregulation is associated with pruritus in the skin of uremic pruritus patients." (PMID 40443235, 2025). "Our experiments argue for a determining role of TNF-α and IL-6 in DM-associated pruritus, and further experiments are required to study the role of PPAR-γ." (PMID 37250649, 2023). "The aim of the study was to assess the frequency of IL-6 gene polymorphisms in CTCL patients, relationship between IL-6/STAT3 gene polymorphisms and IL-6 serum level and clinical values such as stage of the disease and pruritus." (PMID 32270320, 2021). "The aim of the study was to assess the frequency of IL-6 -174 G/C gene polymorphisms in CTCL patients, relationship between IL-6 gene polymorphisms, IL-6 serum level and clinical values such as stage of the disease or pruritus intensity." (PMID 32270320, 2021). "Presence of IL6 GG genotype significantly increased the risk of mild pruritus (OR = 0.41, CI 0.18–0.92, p = 0.03)." (PMID 32270320, 2021). "Presence of IL-6 CC genotype significantly increases the risk of severe pruritus (OR = 2.63, 95% CI 1.05–6.59, p = 0.04)." (PMID 32270320, 2021). "Our results argue that cutaneous disease activity, TNF-α, and IL-6 might play a central role in DM-associated itch, while TRPV4 plays a central role in tissue regeneration." (PMID 37250649, 2023). "However, since IL-6 is involved in most systemic inflammatory responses, IL-6 cannot be a specific factor for CKD-associated pruritus." (PMID 36675074, 2023). "We examined the expression and secretion of IL-31 and IL-6 in microglia and our findings suggest that the elevation of IL-31 and IL-6 levels in CNS could play a direct role in exciting other cells of CNS to cause pruritus." (PMID 40443235, 2025). "In the current study, the inhibitory effect of DHS on pruritus was investigated in lipopolysaccharide (LPS)-stimulated microglia, IL-31- and IL-6-treated astrocytes, and chloroquine-treated mice." (PMID 40443235, 2025). "Vitamin D has been shown to downregulate the production of pro-inflammatory cytokines, such as TNF-α, IL-6, and hs-CRP, which are often elevated in conditions associated with chronic pruritus." (PMID 39337471, 2024). "Serum IL-6 levels are significantly elevated in patients with PN and are correlated with the severity of pruritus." (PMID 38077377, 2023). "IL-31 belongs to the IL-6 cytokine family, which can directly trigger pruritus in humans and is called “itch cytokine”." (PMID 38077377, 2023). "Pruritus scoring, skin moisture, plasma IL-6, and cardiometabolic parameters were measured at baseline, and at the first, second, and third month post-supplementation with fish oil for assessment of the clinical significance." (PMID 35744059, 2022). "IL-6 was related to the pruritus transduction in prurigo nodularis and calcium phosphate-induced pruritus." (PMID 35885674, 2022). "In the present study, we found that supplementation with omega-3 PUFA significantly decreased both the plasma CRP and IL-6 levels, as well as the consequent severity of pruritus in hemodialysis patients." (PMID 35744059, 2022). "The CTCL group with genotype GG of IL-6 gene presented significantly lower mean pruritus intensity compared to other genotypes (NRS p = 0.02/VAS p = 0.05)." (PMID 32270320, 2021). "The distinction between the genotype frequency of IL-6 gene polymorphism in different stages of CTCL and pruritus intensity was also examined." (PMID 32270320, 2021). "Some cytokines, such as IL-6, are correlated with night pruritus and sleeping quality of AD patients." (PMID 33172083, 2020). "In this study, we provide the data to demonstrate that skin C. acnes plays a pivotal role in the signaling of CaP-induced pruritus mediated by IL-6/p-ERK." (PMID 31979095, 2020). "Overall, data in our publication have shown that CaP-induced pruritus was mediated by the IL-6/p-ERK signaling in mice." (PMID 31979095, 2020).
Pruritus (continued). "DHS was shown to suppress pruritus-related cytokines IL-31 and IL-6 in LPS-treated microglia." (PMID 40443235, 2025). "The objective of this study is to investigate the effects of oral supplementation with omega-3 polyunsaturated fatty acid (omega-3 PUFA) on circulating interleukin-6 (IL-6), cardiometabolic parameters, skin moisturization, and the consequent symptoms of pruritus in hemodialysis patients." (PMID 35744059, 2022). "This hypothesis was supported by the elevated serum levels of the C-reactive protein (CRP) and the inflammatory cytokines interleukin (IL)-2 and IL-6 in HD patients with pruritus versus those free from pruritus." (PMID 35324695, 2022). "Topical application of Danggui (Angelica sinensis) has been reported to attenuate inflammation and severity of pruritus symptoms by reducing the number of mast cells, serum IgE concentrations, and by reducing the concentration of inflammatory cytokines, such as IL-6, TNF-α, and IFN-γ." (PMID 36297351, 2022). "The aim was to examine whether IL-6 cytokine and polymorphisms of IL-6 and STAT3 gene are associated with CTCL susceptibility, stage of disease and pruritus intensity." (PMID 32270320, 2021). "Lower C. acnes count with increased IL-6 level are major problems in CKD patients with pruritus." (PMID 31979095, 2020). "The vaccination of PRV-ΔgE/ΔgI/ΔTK-(CD2v) causes neither pruritus, not a systemic infection and inflammation (with the high expression of interleukin-6 (IL6))." (PMID 33198749, 2020). "Topical application of fermenting C. acnes, butyric acid or BA-NH-NH-BA onto mouse skin effectively ameliorated CaP-induced skin itching, interleukin (IL)-6 up-regulation in keratinocytes, and extracellular signal-regulated kinase (ERK) 1/2 activation in dorsal root ganglia (DRG)." (PMID 31979095, 2020). "Topical application of BA-NH-NH-BA onto the skin of CaP-injected mice significantly resulted in a decrease in pruritus with significant down-regulation of IL-6, highlighting the potential of developing fermentation metabolites as postbiotics for treatments of uremic pruritus." (PMID 31979095, 2020). "BA-NH-NH-BA, a butyric acid derivative, may inhibit HDAC to activate AcH3K9 in keratinocytes to block the signaling of CaP-induced skin itching mediated by IL-6 and p-ERK 1/2." (PMID 31979095, 2020). "Vitamin D has been shown to suppress the production of pro-inflammatory cytokines such as IL-6, TNF-α, and IL-17 while promoting regulatory T-cell activity, thereby reducing skin inflammation and pruritus intensity." (PMID 40332575, 2025). "Previous studies have demonstrated that the serum concentration of pro-inflammatory cytokines, such as interleukin-6 or 2, is higher in ESRD patients with pruritus." (PMID 38385990, 2024). "Simultaneously, CGRP stimulates keratinocyte proliferation but also prompts the release of CGRP, interleukin-1β (IL-1β), IL-6, and tumor necrosis factor-alpha (TNF-α), leading to conditions such as rash and pruritus." (PMID 39144633, 2024). "The hemodialysis patients with pruritus showed higher levels of serum CRP, IL-6, IFN-γ, and CXCR3 producing CD4 cells." (PMID 36675074, 2023). "In vitro studies have shown that aloe vera gel reduces cytokine levels such as IL-6 and TNF-α, while clinical trials support its effectiveness in alleviating itch and inflammation in conditions like seborrheic dermatitis and sunburn-induced pruritus." (PMID 41166019, 2025). "Although TNF-α and IL-6 are not considered the primary cytokines in classic pruritus pathways, they are part of the broader inflammatory network involved in various pruritic conditions." (PMID 40332575, 2025). "Therefore, the current study aimed to evaluate the efficacy of DHS on LPS-induced microglia activation and IL-6-and IL-31-induced astrocyte activation, and also to determine the efficacy of DHS on chloroquine-induced pruritus in mice." (PMID 40443235, 2025).
Pruritus (continued). "First, patients undergoing hemodialysis who develop pruritus with no obvious visible signs of inflammation have significantly higher serum levels of C-reactive protein, IL-6, IFN-γ, IL-2, and IL-31 than patients without pruritus." (PMID 40596915, 2025). "The elevated levels of IL-6 were detected in patients with severe uremic pruritus in comparison with uremic patients without pruritus." (PMID 37250649, 2023). "Other itch mediators such as IL-6, IL-33, and IL-31 may be involved in the mechanism of CLE-related pruritus." (PMID 35885674, 2022). "Here we show that C. acnes fermentation can influence CaP-induced IL-6 in skin and ERK 1/2 activation in DRG through epigenetic mechanisms and that a synthesized butyric acid derivative can efficiently attenuate CaP-induced inflammation and pruritus." (PMID 31979095, 2020). "Furthermore, pruritus severity, irrespective of acute or chronic etiology, is potentiated by additional mediators, including serotonin and interleukin-6 (IL-6)." (PMID 41166019, 2025).
viral pneumonia (26 papers, 2017 to 2026). Inflammation of the lung parenchyma that is caused by a viral infection. "For instance, in patients with viral pneumonia presenting with a cytokine storm, an IL-6 concentration > 300 pg/ml combined with a PaO2/FiO2 ratio < 200 mmHg supports the use of tocilizumab plus baricitinib." (PMID 41521316, 2026). "Viral pneumonia has been predicted by IL6, IL27, and CRP, with distinct cytokine expression profiles differentiating viral from bacterial community-acquired pneumonia." (PMID 41373577, 2025). "In the viral pneumonia group, the IL-6 concentration in BALF was higher than that in blood (P = 0.046); however, HBP concentrations and N% did not significantly differ between the two groups (P > 0.05)." (PMID 36910136, 2023). "The binding energies of isochlorogenic acid B with the six targets, namely, 3CL, ACE2, COX2, HA, IL-6, and NA, were all less than −7 kcal/mol, suggesting that these components play a key role in the treatment of viral pneumonia with LHQW." (PMID 35145559, 2022). "COX2 and IL-6 were the most important common targets of LHQW against viral pneumonia, and the material basis of intervention was the same." (PMID 35145559, 2022). "For instance, patients with viral pneumonia may exhibit a systemic increase in IL-6 levels alongside lung-localized T-cell exhaustion, the latter of which is characterized by programmed cell death protein-1 (PD-1) upregulation and driven by viral persistence." (PMID 41521316, 2026). "In the present study, we demonstrated that bitter apricot kernel is indispensable for the in vivo efficacy of XCD in mitigating viral pneumonia, as its removal abrogated the formula’s ability to reduce the lung index, alleviate hemorrhage and edema, and suppress IL-6 transcription." (PMID 41034926, 2025). "Secondly, procalcitonin, despite being a biomarker with a better predictive value compared to CRP or interleukin-6 in differentiating between bacterial and viral pneumonia, still has a rather low reported sensitivity and specificity, of 0.55 and 0.76, respectively." (PMID 36671345, 2023). "Similarly, IL-6’s cutoff value at 6.1 pg/mL, demonstrating an AUC of 0.869, highlighted its strong predictive power, consistent with its recognized role in orchestrating prolonged inflammatory responses in viral pneumonias." (PMID 39202577, 2024). "This study was performed to demonstrate the effects of methylprednisolone (MPS) and azithromycin treatment on serum biochemical factors and their impact on Serum Biochemical Factors (CRP, PCT, IL-6, TNF-a) prognosis in patients with viral pneumonia (VP)." (PMID 40821637, 2025). "In previous work, we have also discovered increased serum level of IL-10, IL-6, as well as acute-phase proteins (CRP and Serum amyloid A1) in the same patients with SARS-CoV-2 induced viral pneumonia." (PMID 36298646, 2022). "IL-6 blockade is the standard treatment for CAR-T and viral pneumonia." (PMID 41521316, 2026). "ELISA results showed that XCH treatment could decrease levels of BALF IL-6, IL-1β, and TNF-α in mice with viral pneumonia." (PMID 35865338, 2022). "Moreover, EA extract inhibits the overproduction of inflammatory cytokines, including IL-6, TNF-α and MCP-1, in mice induced by viral pneumonia." (PMID 36431955, 2022). "Other cytokines such as IL‐8, IL‐6, interferon‐γ, CXCL10 and CXCL13 may be impacted by ozanimod, which aligns with the ability of S1P1 modulators to decrease inflammatory cytokines during viral pneumonia as seen in preclinical models." (PMID 40025871, 2025). "Finally, threefold cross-validation was performed using a Random Forrest (RF) algorithm, with all combinations of IL-6, LIGHT, and MMP-2, to determine which combinations could most accurately predict whether a patient had viral or non-viral pneumonia." (PMID 41488910, 2025).
viral pneumonia (continued). "In cerebral and pulmonary tissues, the P9 virus replication induced the production of G-CSF, IFN-γ, IL-6, CXCL1, MCP-1, MIP-1α, RANTES, IP-10, MIP-1β, and TNF-α, as well as pathological alterations including reduction of neuronal cells and typical symptoms of viral pneumonia." (PMID 35755996, 2022).
airway hyperresponsiveness (25 papers, 2008 to 2026). "This immunoregulatory action might have resulted in a reduction of inflammation and airway hyperresponsiveness associated with the downregulation of IL-5, IL-6, and IL17." (PMID 23533467, 2013). "The results showed that IL-6 and IL-35 played an important role in inflammatory response and airway hyperresponsiveness." (PMID 34721824, 2021). "IL-6 is a proinflammatory cytokine and involves Th2/Th17-mediated airway inflammation and promotes airway hyperresponsiveness (AHR)." (PMID 30890137, 2019). "IL-13, IL-1 β, IL-6, IL-4, IL-5 are Th2 cell-type factors, mainly involved in mucus secretion, eosinophil production, IgE synthesis, and airway hyperresponsiveness." (PMID 31024302, 2019). "IL-6 is produced by a wide variety of cell types and is known to contribute to Th2 cytokine production, lung eosinophilia, and airway hyperresponsiveness." (PMID 29854835, 2018). "IL-6 has been shown to enhance collagen synthesis, production of tissue inhibitors of metalloproteinases (TIMPs), and airway hyperresponsiveness." (PMID 24782592, 2014). "The combination of IL-6 and IL-8 is frequently used in ARDS research, whereas IL-13 was only present in combination with high IL-5 concentrations; both are T-helper cell 2 cytokines associated with airway hyperresponsiveness." (PMID 31998415, 2020). "They found that in female mice, gonadectomy reduced ozone-induced airway hyperresponsiveness (AHR) and lung interleukin 6 (IL-6) expression." (PMID 38419020, 2024). "Amox- and TMP/SMX-treated animals displayed more severe allergic airway inflammation parameters with increased airway hyperresponsiveness, reduced lung alveolar volume, and increased levels in BAL of IL-4 and IL-6." (PMID 35785028, 2022). "Airway hyperresponsiveness as well as levels of IFN-γ, IL-13, IL-6, and IL-10 was lower in the lungs of asthmatic March1−/− mice compared to WT, whereas lung levels of TNF-α, IL-4, and IL-5 were not significantly different." (PMID 29854835, 2018). "Our data show that Miro1 suppresses epithelial induction and maintenance of the inflammatory response to allergen, as Miro1 deletion modestly induces increases in pro-inflammatory signaling, specifically IL-6, IL-33, CCL20 and eotaxin levels, tissue reorganization, and airway hyperresponsiveness." (PMID 37377691, 2023). "IL-6, VEGFA, and AHR interact to induce eosinophilic airway inflammation, mucinous metaplasia, subepithelial fibrosis, myocyte proliferation, and dendritic cell activation, leading to airway hyperresponsiveness and angiogenesis of airway remodeling." (PMID 32015750, 2020). "Therefore, through modulation of these TH2 cytokines, such as IL-5, IL-6, and IL-13, KWLL treatment was able to reduce eosinophils infiltration and airway hyperresponsiveness." (PMID 23533467, 2013). "DiABZI administration during HDM challenge increased airway hyperresponsiveness, neutrophil recruitment with prominent NOS2+ARG1− type 1 neutrophils, protein extravasation, cell death by PANoptosis, NETs formation, extracellular dsDNA release, DNA sensors activation, IFNγ, IL‐6 and CXCL10 release." (PMID 39466641, 2025). "PAI‐1 regulates expression of interleukin (IL)‐6, keratinocyte chemoattractant (KC), and macrophage inflammatory protein (MIP)‐2, which are cytokines that promote lung injury, pulmonary inflammation, and/or airway hyperresponsiveness following acute exposure to O3." (PMID 27670409, 2016).
autoimmune thyroid disease (25 papers, 2007 to 2025). Inflammatory disease of the thyroid gland due to autoimmune responses leading to lymphocytic infiltration of the gland. "TPO-Ab positivity, often used as a marker of thyroid autoimmunity, has been associated with elevated pro-inflammatory cytokines, including interleukin-6 (IL-6) and tumour necrosis factor-alpha (TNF-α), which can have systemic effects beyond the thyroid gland." (PMID 40756512, 2025). "IL-4 and IL-6 have also been implicated in autoimmune thyroid." (PMID 37513704, 2023). "Fat accumulation is linked with elevated TSH levels, and excess adiposity can affect thyroid autoimmunity by increasing the levels of adipokines such as leptin and IL6, which are crucial for maintaining immune homeostasis." (PMID 40218202, 2025). "Chronic inflammation in autoimmune thyroid disease is characterized by elevated pro-inflammatory cytokines (e.g., IL-6, TNF-α), which can suppress hepatic enzyme production or alter their release kinetics." (PMID 40978853, 2025). "Other studies have noted elevated IL-6 during destructive thyroiditis and increased activation of Th1-like peripheral lymphocytes in autoimmune thyroiditis." (PMID 40735669, 2024). "In this study, it was observed that IL-6 levels were elevated in live-birth women with recurrent spontaneous abortions who had thyroid autoimmune." (PMID 38298186, 2023). "Gallic acid decreases the expression of the interleukin 6 (IL-6) gene, inhibiting the differentiation of T helper 17 (Th17) cells that intervene in the pathogenesis of autoimmune thyroid diseases (AITDs)." (PMID 37161471, 2023). "Recently, in patients with autoimmune thyroiditis, increased IL-6 and IL-15 (another pro-inflammatory cytokine) were detected, likely due to increased proliferation and increased pro-inflammatory cytokine synthesis in T-helper 17 cells." (PMID 26100072, 2015). "Adipose tissue is an active endocrine organ that secretes pro-inflammatory cytokines such as TNF-α, IL-6, and leptin, which may exacerbate thyroid autoimmunity and contribute to ovarian dysfunction." (PMID 41303060, 2025). "Leptin-induced inflammation and the presence of inflammatory cytokines like TNF-α and IL-6 within the thyroid gland may contribute to the development of thyroid autoimmunity." (PMID 38567309, 2024). "In anti-tumor immunity, GM-CSF treatment increases the frequency of tumor-specific Th1 T cells, and, in experimental autoimmune thyroiditis, GM-CSF treatment has been shown to both enhance IL-6–dependent Th17 cell responses and increase the number of immunoregulatory CD4+CD25+ T cells." (PMID 35877763, 2022). "Notably, this phenotype is also associated with increased levels of thyroid autoimmunity markers, such as thyroid autoimmunity (TPO antibodies) and the inflammatory markers CRP and IL-6." (PMID 39749338, 2024).